SNHG1 (small nucleolar RNA host gene 1)
Diseases named in the same sentence as SNHG1 in open-access papers (continued):
Sharing a sentence is not in itself a finding about the gene and the disease.
neuroblastoma (18 papers, 2016 to 2025). Neuroblastoma (NB) is the most common solid, extracranial childhood tumor. "In neuroblastoma, high SNHG1 expression is associated with poor survival and is upregulated by MYCN amplification." (PMID 37464317, 2023). "Functionally, RES resulted in the promotion of cell autophagy in MPP+-induced human neuroblastoma cells, while these influences were abolished by SNHG1 overexpression." (PMID 37626481, 2023). "The miR-128-3p inhibitor reversed the SNHG1 knockdown-mediated promotion of cell autophagy in MPP+-induced human neuroblastoma cells." (PMID 37626481, 2023). "As expected, SNCA overexpression abolished the SNHG1 knockdown-mediated promotion of cell autophagy in MPP+-induced human neuroblastoma cells upon RES pre-incubation." (PMID 37626481, 2023). "SNHG1 and PLK4 were increased in neuroblastoma tissue and cells, whereas the expression of miR‐338‐3p decreased and targets of miR‐338‐3p and SNHG1 or PLK4 were elucidated." (PMID 35592755, 2022). "Of note, SNHG1 expression was evidently elevated in MPP+-induced human neuroblastoma cells." (PMID 37626481, 2023). "Moreover, SNCA overexpression reversed SNHG1 silencing-induced cell autophagy in MPP+-induced human neuroblastoma cells upon RES pre-incubation." (PMID 37626481, 2023). "The lncRNA small nucleolar RNA host gene 1 (SNHG1) is downregulated under hypoxia conditions in neuroblastoma, SH-SY5Y cells, inhibiting cell viability and promoting cell apoptosis through the suppression of Bcl-XL as an anti-apoptotic protein via targeting miR-140-5p." (PMID 33321920, 2020). "We previously found highly expressed SNHG1 was associated with poor prognosis and MYCN status in neuroblastoma (NB)." (PMID 36130928, 2022). "A previous study revealed a strong negative correlation between SNHG1 expression and survival time in patients with high-risk neuroblastoma (NB)." (PMID 33499863, 2021). "The authors revealed correlation between SNHG1 regulation and MYCN amplification and suggested SNHG1 as another indicator of neuroblastoma patient’s outcome and/or as an option for therapeutic targeting." (PMID 28178969, 2017). "We next investigated their expression levels in different stages of NB based on the International Neuroblastoma Staging System (INSS) and discovered that, as compared to stages 1–3, SNHG1 showed a significant higher expression in stage 4." (PMID 27517149, 2016). "Current results suggest SNHG1 is a critical coregulator but not a member of the ADRN neuroblastoma CRC." (PMID 36130928, 2022). "Therefore, SNHG1 may interplay with HDAC1/2 and coordinately mediate the transition of neuroblastoma cell fate." (PMID 36130928, 2022). "Moreover, SNHG1, miR-128-3p and SNCA were also indicated by our study to be regulated by RES, and it was further found that RES could promote autophagy by regulating the SNHG1/miR-128-3p/SNCA regulatory axis, thereby protecting human neuroblastoma cells and preventing PD." (PMID 37626481, 2023).
osteosarcoma (18 papers, 2019 to 2026). A usually aggressive malignant bone-forming mesenchymal neoplasm, predominantly affecting adolescents and young adults. "LncRNA small nucleolar RNA host gene 1 (SNHG1), one of dysregulated lncRNAs in multiple cancer, is shown to be also involved in pathology of osteosarcoma." (PMID 34130697, 2021). "SNHG1 is highly expressed in osteosarcoma and positively correlated with tumor size, TNM stage and lymph node metastasis." (PMID 34130697, 2021). "SNHG1 was also found to be highly expressed in posterior longitudinal ligament patients, cholangiocarcinoma, and osteosarcoma." (PMID 33499863, 2021). "For instance, SNHG1, a novel oncogenic lncRNA with abnormal expression in various cancer types, can contribute to osteosarcoma tumorigenesis and progression via complex mechanisms." (PMID 34733885, 2021). "Long non-coding RNA small nucleolar RNA host gene 1 has been previously reported to regulate the NOB1 expression by binding to miR-326 in osteosarcoma." (PMID 32670874, 2020). "More and more evidences showed that the dysfunction of SNHG1 is related to the occurrence and development of human diseases, such as OA, osteosarcoma, colorectal carcinoma, and liver cancer." (PMID 31383786, 2019). "In the future, we will further explore whether IGF2BP3 functions as a downstream effector that mediates the m6A-dependent stabilization of SNHG1 in osteosarcoma." (PMID 40510136, 2025). "Among these lncRNAs, SNHG1 promotes osteosarcoma progression via miR-493-5p as an oncogenic factor." (PMID 35692813, 2022). "Interestingly, SNHG1 seems to play a very important role in the development of osteosarcoma through the ceRNA mechanism, suggesting that SNHG1 may have a unique role in the relationship between tumor and bone microenvironment." (PMID 41507135, 2026). "However, the role of METTL3 and small nucleolar RNA host gene 1 (SNHG1) playing in osteosarcoma (OS) remains largely unknown." (PMID 40510136, 2025). "Moreover, up-regulated SNHG1 could exert an oncogenic role in osteosarcoma, contributing to tumor progression and poor prognosis in osteosarcoma patients." (PMID 34806925, 2021). "Besides, it is reported that SNHG1 increased the expression of human oncogene nin-one binding protein (nob1) by sponging miR-326 as ceRNA, and ultimately promoted the growth, migration, and invasion of osteosarcoma cells." (PMID 31383786, 2019). "Recent studies have shown SNHG1, SNHG5, SNHG16, and SNHG20 to be overexpressed in osteosarcoma tissues and play vital roles in promoting tumour progression." (PMID 37278038, 2023). "Prior studies have confirmed that lncRNAs such as LINC00689, SNHG1 and HOST2 are markedly overexpressed in osteosarcoma tissues and cells." (PMID 35123530, 2022). "In osteosarcoma, small nucleolar RNA host gene 1 (SNHG1) regulates the level of NIN1 binding protein 1 homolog (NOB1) by sponging miR-326 and promotes the tumorigenesis of osteosarcoma cell." (PMID 32425696, 2020). "The long noncoding RNA (lncRNA) small nucleolar RNA host gene 1 (SNHG1), located in the 11q12.3 region of the chromosome (GenBank accession ID: 23642), was aberrantly upregulated in several cancers and promotes malignant progression in lung, osteosarcoma, and liver." (PMID 41507135, 2026). "lncRNA DARS-AS1 promotes the progression of osteosarcoma by regulating miR-532-3p/CCR7; lncRNA BACE1-AS regulates the proliferation, migration, and invasion of osteosarcoma cells through the miR-762/SOX7 axis; lncRNA SNHG1 promotes osteosarcoma progression by upregulating S100A6 through miR-493-5p." (PMID 36388161, 2022).
Parkinson disease (14 papers, 2020 to 2025). A progressive degenerative disorder of the central nervous system characterized by loss of dopamine producing neurons in the substantia nigra and the presence of Lewy bodies in the substantia nigra and locus coeruleus. "SNHG1 has been found to be upregulated in Parkinson’s disease (PD), where it acts as a sponge for several miRNAs, including miR-7, miR-125b-5p, miR-181a-5p, and miR-221/222/p27." (PMID 38920691, 2024). "It was found that SNHG1 in in vitro PD models improves neuronal apoptosis with miR-153-3p blocking, and promotes the progression of Parkinson’s disease by inhibiting PI3K/Akt83." (PMID 38472261, 2024). "Actually, the regulatory action of lncRNA Snhg1 on cell viability has also been demonstrated in multiple disorders, such as cancers, Parkinson’s disease, and hypoxic injury." (PMID 38796415, 2024). "The long noncoding RNA small nucleolar RNA host gene 1 (SNHG1) is another newly identified lncRNA that was found to be upregulated in the brain specimens derived from patients with Parkinson’s disease (PD) and in MPTP-induced PD mouse models." (PMID 37189549, 2023). "Mechanistically, miR-181a-5p inhibition regulates cell survival in neurons and astrocytes after forebrain ischemia and stroke, and lncRNA SNHG1 promotes neuronal injury in a Parkinson’s disease cell model via the miR-181a-5p/CXCL12 axis." (PMID 36998510, 2023). "LincRNA-p21, SNHG1 and HOTAIR have been linked to Parkinson’s disease (PD)." (PMID 39920595, 2025). "Additionally, lncRNA NEAT1 impacts Parkinson’s disease pathology by sponging miR-212-3p, which targets AXIN1, while lncRNA SNHG1 exacerbates neuroinflammation in Parkinson’s disease through the miR-7/NLRP3 pathway." (PMID 39280701, 2024). "Silencing of SNHG1 promoted neuronal autophagy and prevented cell death in Parkinson's disease." (PMID 34621163, 2021). "Similarly, Cao’s study found that long noncoding RNA small nucleolar RNA host gene 1 promoted neuroinflammation in the pathogenesis of Parkinson’s disease via modulating miR-7/NLRP3 pathway." (PMID 31959187, 2020). "For instance, a study showed that SNHG1 was remarkably elevated in LPS-induced BV2 cells, and its depletion mitigated neuroinflammation through the miR-7/NLRP3 axis in Parkinson’s disease." (PMID 35547731, 2022). "Bioinformatics analysis demonstrated that lnc-RNA SNHG1 and mRNA NLRP3 shared the same region to interact with miR-7 in Parkinson’s diseases, suggesting that SNHG1 competes with NLRP3 for binding with miR-7." (PMID 34439798, 2021). "In particular, the overexpression of SNHG1 has been reported to compete endogenous RNA for miR-7 to regulate NLRP3 expression, leading to the activation of the NLRP3 inflammasome and promoting neuroinflammation in Parkinson’s disease." (PMID 35547731, 2022). "Therefore, interaction between miR-7 and SNHG1 leads to elevate NLRP3 expression, resulting in NLRP3 inflammasome activation in Parkinson’s patients." (PMID 34439798, 2021).
liver cancer (13 papers, 2017 to 2026). An epithelial or non-epithelial malignant neoplasm that arises from the liver. "Besides, a prior work elucidated that ectopically expressed lncRNA SNHG1 could accelerate the progression of liver cancer, for which cirrhosis is a significant risk factor." (PMID 35194023, 2022). "Moreover, SNHG1 has been documented to be implicated in liver disease, like liver cancer." (PMID 35194023, 2022). "Analysis of clinical samples revealed that the expression levels of SNHG1, SNHG3‐7, SNHG16, SNHG20, and MEG8 (Maternally expressed 8, also known as SNHG23) are associated with clinical indicators of liver cancer patients." (PMID 41474641, 2026). "Inhibition of SNHG1 results in the suppression of sorafenib-resistant tumors in vivo, while knockdown of SNHG1 in liver cancer cell lines renders cells more sensitive to sorafenib." (PMID 39200161, 2024). "In contrast, the lncRNA SNHG1 has a certain potential for use in the development of liver cancer therapy as a biomarker of sorafenib resistance." (PMID 36980210, 2023). "Although the SNHG1 gene plays an important oncogenic role in liver cancer, this is also the case for most cancers, including colorectal, cervical, and colon cancers." (PMID 36980210, 2023). "Consistently, SNHG1 was also determined to be highly expressed in liver cancer cell lines (HepG2, SMMC-7721, HuH-7, and Li-7) as compared with normal liver cells HL-7702." (PMID 34095464, 2021). "Among those liver cancer cell lines, HepG2 and HuH-7 cell lines exhibited relatively higher expression of SNHG1; therefore, HepG2 and HuH-7 cells were selected for subsequent experiments." (PMID 34095464, 2021). "Also, the expression of lnc-SNHG1 was significantly upregulated in liver cancer tissues and liver cancer cell line compared with normal liver tissue and cell line; the overexpression of lnc-SNHG1 promoted the proliferation, invasion, and migration of liver cancer cells through binding to miR-195." (PMID 33302997, 2020). "Additionally, some in vivo experiments indicated that SNHG1, SNHG5, SNHG6, SNHG8, DANCR, SNHG16, and SNHG17 can promote lung metastasis of human liver cancer cells in immunodeficient mice." (PMID 41474641, 2026). "Liver malignant neoplasms with a higher expression of SNHG1 exhibit a significantly lower TNB, as opposed to those with lower expression of SNHG1, which can partially explain why HCC with higher SNHG1 expression can display greater resistance to therapy." (PMID 39200161, 2024).
cervical cancer (10 papers, 2019 to 2022). A primary or metastatic malignant neoplasm involving the cervix. "lncRNA Small Nucleolar RNA Host Gene 1 (SNHG1), located at chromosome 11q12.3, reportedly plays an oncogenic role in diverse cancers, such as colorectal, breast, and cervical cancers." (PMID 35836822, 2022). "For instance, SNHG1 expression is elevated in cervical cancer (CC) cells and tissues, and down-regulation of SNHG1 in vitro can significantly restrain CC cell proliferation, migration and invasion." (PMID 35435130, 2022). "Recently, SNHG1 was reported to be highly expressed in cervical cancer and knock-down of SNHG1 decreased migration and invasion of cancer cells." (PMID 33777808, 2021). "SNHG1 is a lncRNA whose expression correlates with aggressive cervical cancer by promoting tumor cell proliferation, migration and invasion." (PMID 33291485, 2020). "Moreover, it was also seen that SNHG1 enhances invasiveness and proliferation in cervical cancer However, the potential of SNHG1 is still elusive." (PMID 34712495, 2021). "Consequently, SNHG1 depletion reduced metastatic lesions in cervical cancer." (PMID 33291485, 2020).
colon cancer (10 papers, 2019 to 2025). "In colon cancer, SNHG1/miR-154-5p/EZH2 regulatory axis promotes the growth of colon cancer cells by regulating cell cycle-related signaling pathways." (PMID 38811958, 2024). "Research has revealed that the expression of SNHG1 is significantly increased in both colon cancer tissues and cell lines when compared with that in the normal samples." (PMID 37684619, 2023). "One group identified that small nucleolar RNA host gene 1 (SNHG1) expression is overexpressed in colon cancer cells and tumor specimens." (PMID 33246471, 2020). "SNHG1 accelerates cell proliferation via upregulating β-catenin, c-Myc and cyclin D1 protein levels in colon cancer cells." (PMID 33246471, 2020). "SNHG1 overexpression inhibits colon cancer cell apoptosis possibly via the Wnt/β-catenin signaling pathway." (PMID 33246471, 2020). "In addition, SNHG1 exhibited potentials in regulating the initiation and metastasis of colon cancer via cell cycle signaling pathway by working as a miR-484-mediated ceRNA of ORC6." (PMID 33194594, 2020). "As lncRNAs KCNQ1OT1 and SNHG1 exhibited high potential in diagnosing patients with colon cancer or rectal cancer, we further validated their experimental gene expression pattern and diagnostic performance via published GEO datasets including GSE21510, GSE23878, and GSE9348." (PMID 33194594, 2020). "Higher SNHG1 expression indicated a poor prognosis in colon cancer." (PMID 31691514, 2019). "Therefore, SNHG1 may be a potential biomarker for colon cancer and has the potential to serve as a new therapeutic target." (PMID 37684619, 2023). "Although SNHG1 or KCNQ1OT1 has been reported to be significantly correlated with the prognosis of colon cancer, the regulatory mechanism of SNHG1 or KCNQ1OT1 underlying the pathogenic differences between colon cancer and rectal cancer has not been well explored." (PMID 33194594, 2020). "The overexpression of SNHG1 has been shown to enhance cell proliferation, invasion, migration, and EMT progression in colon cancer." (PMID 37684619, 2023).
esophageal cancer (9 papers, 2017 to 2024). A primary or metastatic malignant neoplasm involving the esophagus. "For instance, SNHG1 acts as an undegradable sponge for the tumor suppressor miR-338 within esophageal cancer cells, thus promoting cell proliferation." (PMID 38706912, 2024). "Snhg1 promotes expression of proto-oncogene CST3 by acting as a sponge for miR-338 in primary esophageal cancer cells." (PMID 29416759, 2018). "Then Snhg1 was overexpressed by the pcDNA-Snhg1 or silenced by the Snhg1 siRNA transfection in the primary esophageal cancer cells." (PMID 28423738, 2017). "Snhg1 promoted cell proliferation by acting as a sponge for the tumor suppressor miR-338 in esophageal cancer cells." (PMID 29029488, 2017). "SNHG1 was significantly upregulated in esophageal cancer tissues." (PMID 31691514, 2019). "Additionally, SNHG1 was reported to act as a sponge for miR-338 to enhance esophageal carcinoma cell growth." (PMID 29416759, 2018). "In our research, we discovered that 3 lncRNAs from SNHG family (SNHG1, SNHG7, and SNHG12) were upregulated in ESCA (esophageal carcinoma) tissues based on Cancer RNA‐Seq Nexus analysis." (PMID 32239639, 2020). "In esophageal cancer, SNHG1 was reported to act as a non-degradable sponge for miR-338 to promote esophageal carcinoma cell growth." (PMID 29416759, 2018).
lymph node metastasis (9 papers, 2017 to 2024). "Increased SNHG1 expression was significantly associated with lymph node metastasis (OR = 3.28, 95% CI = 2.02–5.33) and advanced TNM stage (OR = 0.26, 95% CI = 0.16–0.43)." (PMID 31008944, 2019). "Various clinicopathological features and prognoses of cancer, including tumor lymph node metastasis (TNM) stage, lymph node metastasis, and overall survival (OS), have been observed to be positively correlated with the upregulation of SNHG1." (PMID 37684619, 2023). "Several clinicopathological features and prognoses, such as OS, TNM stage, and lymph node metastasis of patients, have been shown to be significantly correlated with the abnormal expression of SNHG1." (PMID 37684619, 2023). "As mentioned, upregulated SNHG1 expression was significantly positively correlated with lymph node metastasis (P = .033) and advanced TNM stage (P = .01)." (PMID 31469189, 2019). "High expression of SNHG1 in NSCLC patients was associated with larger tumor size, advanced TNM stage, lymph node metastasis and poor overall survival." (PMID 28147312, 2017). "Univariate analysis displayed that a few prognosis factors (distant metastasis, depth of invasion, lymph node metastasis, venous invasion, nervous invasion, obstruction, TNM stage, tumor diameter and SNHG1 expression) were statistically significant risk factors influencing OS and PFS of patients." (PMID 29340086, 2017). "The current study found that SNHG1 expression positively correlates with advanced TNM stage (III and IV) and the presence of lymph node metastasis." (PMID 31469189, 2019). "High SNHG1 expression was more frequently to be detected in tumors with bigger tumor diameter (P=0.012), advanced TNM stage (P=0.004), lymph node metastasis (P=0.011), deep invasion (P=0.009)." (PMID 29340086, 2017). "In addition, the level of SNHG1 was markedly upregulated in patients with lymph node metastasis (N1/2) group, compared with patients without lymph node metastasis (N0) group." (PMID 31469189, 2019).
pancreatic cancer (9 papers, 2019 to 2023). "For instance, a prior study also reported the tumor-promoting potential of SNHG1 in pancreatic cancer with the results that SNHG1 silencing triggered repression of cell proliferative, metastatic, and invasive capacities by inactivating Notch-1 pathway." (PMID 36230661, 2022). "Moreover, SNHG1 suppresses pancreatic cancer cell proliferation, invasion and metastasis through inhibiting the Notch-1 signaling pathway." (PMID 31615767, 2019). "A coexpression network revealed a hub comprising lncRNAs (MIR210HG, SNHG1, and LOC729970) and mRNAs (RAB3D, DDX17, and SPNS2) that presumably mediate drug resistance in pancreatic cancer." (PMID 31399552, 2019). "Furthermore, lncRNAs MALAT1, SNHG1, and RP11-363N22.3 may also play a role in pancreatic cancer via hsa-miR-143-3p." (PMID 33643376, 2021).